MMP9 (matrix metallopeptidase 9)
Diseases named in the same sentence as MMP9 in open-access papers (continued):
Sharing a sentence is not in itself a finding about the gene and the disease.
breast carcinoma (continued). "To expose some molecular mechanisms by which Pax-5 could suppress breast cancer aggressive features, we performed RT-qPCR on molecular mediators of breast cancer malignancy such as: MMP2 and MMP9; vimentin and fibronectin following Pax-5 transfection of MB231 cells." (PMID 28076843, 2017). "It has been proposed that MMP9, a 92 kDa type IV collagenase, exerts its ability as a key mediator of extracellular matrix (ECM) remodeling and metastasis through degradation of type IV and V collagens, and acts as prognostic biomarker for breast cancer patients." (PMID 28212583, 2017). "In addition, SFN suppressed the growth of KPL-1 human breast cancer cells both in vitro and in athymic mice, and the anti-metastatic action of SFN might be through inhibiting MMP-9 expression via the NF-κB signaling pathway." (PMID 28698459, 2017). "Moreover, MMP2 seems to have no prognostic value for breast cancer patients while the prognostic impact of tissue expression or circulating level of MMP9 remains controversial." (PMID 26921265, 2016). "In addition, UDP increased MMP-9 enzyme activity, not only in MDA-MB-231 cells, but also in BT549, T47D, MDA-MB-468, MDA-MB-453 and MCF-7 cells, suggesting the extensive role of UDP/P2Y6 in breast cancer cell metastasis." (PMID 27074554, 2016). "In addition, FN triggers MMP-2 and MMP-9 expression which are involved with cell invasion and migration through binding of RGD sequence of α5β1 integrin in several human carcinoma cells, including breast cancer cells." (PMID 26637807, 2016). "The proteolytic activities of MMP-2 and MMP-9, expressed by macrophages, promote the release of cryptic fragments by cleaving laminin-5 γ2 chains which mimic EGF ligand and induce cell motility and invasion in EGFR overexpressing human breast carcinoma cell lines." (PMID 28053982, 2016). "Our results show a marked increase in MMP-9 expression, as detected by gelatine zymography and real time RT-PCR, when RAW264.7 macrophages are exposed to the M2 polarization-inducing cytokine IL-4 or when they are co-cultured with breast cancer cells in separate chambers." (PMID 26078009, 2015). "Similarly, TGF-β-induced overexpression of MMP-2 and MMP-9 was mediated by p38 MAPK but not by ERK signaling in breast cancer cells." (PMID 23710144, 2013). "The contact of breast cancer cell lines with the microenvironment completely modified their transcriptional programs by increasing the expression of genes involved in cell proliferation (cyclinD1, MAPK), angiogenesis (MMP9, VEGF) and hormonal pathways (ESR1, IL6)." (PMID 23750285, 2013). "In addition, a previous study reported that NDRG2 could inhibit the metastatic potential of breast cancer cells, specifically via the suppression of CD24 or MMP-9 expression." (PMID 23800335, 2013). "Measurement of the MMP-9:TIMP-1 protein:protein complex concentrations in plasma from breast cancer patients for prognostic purposes has not previously been described although numerous publications have indicated that both molecules, when measured individually, are indicative of patient prognosis." (PMID 24330623, 2013). "In another breast carcinoma model, MMP-9 regulation by TGF-β did not require p38MAPK." (PMID 22614218, 2012). "Introduction of HER2 into human MCF-10A breast cancer cells, a non-tumorigenic epithelial cell line, induced MMP-9 up-regulation via p38 mitogen-activated protein kinase (p38 kinase) and Akt signaling pathways that further enhanced the invasive and migratory capacities of MCF-10A cells." (PMID 19617202, 2011). "According to previous studies, the p38 MAPK is a central kinase in a common pathway that plays an important role in breast cancer invasion and metastasis by modulating the expression and activity of molecules involved in the degradation of extracellular matrix (that is, MMP-2 and MMP-9)." (PMID 21167057, 2010).
breast carcinoma (continued). "Furthermore, BER suppresses Akt and nuclear factor κB signaling by reducing the phosphorylation of c-Met and Akt, and inhibiting their downstream targets such as nuclear factor κB p-65, Bcl-2/Bax, osteopontin, VEGF, MMP-9 and MMP-2 on protein and/or mRNA levels in breast cancer cells." (PMID 19796390, 2009). "Moreover, MMP-9/NGAL enzymatic activity was observed in the urine of breast cancer patients but not in healthy controls." (PMID 19889214, 2009). "On the other hand, NGAL and MMP-9/NGAL complex have not yet been evaluated in breast cancer." (PMID 19889214, 2009). "It has also been described that as breast cancer progresses, MMP-2 production increases during the early phases, whereas activation of MMP-9 occurs during the late cancerous stage, which could explain their different impact on prognosis in clinically detected invasive breast tumours." (PMID 17342087, 2007). "Indeed increased MMP-9 expression has been shown to favour survival in node-negative patients with breast cancer." (PMID 17311017, 2007). "However, the association of ERBB2 expression with the expression of MMP-2 and MMP-9 has not previously been reported in breast cancer." (PMID 15054465, 2004). "However, the role of MMP-9 is less clear than that of u-PA, as overexpression of MMP-9 in human breast cancer was reported to be a favourable indicator in node-negative patients." (PMID 12698185, 2003). "The overexpression of MMP-9 in breast cancer may be also used as a marker to subdivide node negative breast cancer patients in order to determine the optimal treatment modality." (PMID 11384099, 2001). "In breast cancer (BC), an anti‐α9‐nAChR/methoxy‐polyethylene glycol (mPEG)‐conjugated bispecific antibody (α9 BsAb) inhibits the expression of VEGF‐A, p‐VEGFR2, VEGFR2, and MMP9, thereby suppressing cell migration." (PMID 41415714, 2025). "In addition to MMP-2 and MMP-9, MMP-1 has also been used as an accurate marker in a three markers scores model, including MMP-1, hepatocyte growth factor, and chemokine ligand 5, to predict axillary lymph node metastasis (LNM) positivity in breast cancer patients." (PMID 37181043, 2023). "In this study, the observed increase in Snail1, Vimentin and MMP-9 expression as well as the reduction in E-cadherin expression in the BT549-liposome-CD147 group suggests that CD147 may contribute to EMT and facilitate tumor invasiveness in certain breast cancer cases." (PMID 38066486, 2023). "In addition, the expression level of E-cadherin was up-regulated and expressions of Vimentin, MMP-2, MMP-9, Slug and Snail were reduced in the xenografts in the KIF3B-shRNA group compared with the control group by IHC staining, which were consistent with the results in breast cancer cell lines." (PMID 33542902, 2020). "Additionally, in human breast cancers no increased levels of extracellular MMP-9 has been detected." (PMID 31475105, 2019). "Finally, Fascin and MMP-9 may represent potential therapeutic targets for patients with breast cancer especially those with hormone receptor–negative status." (PMID 24993803, 2014). "Additionally, miR-206 was identified as tumor suppressor in breast cancer cell lines and was found to mediate this effect by directly targeting cell division cycle 42 (CDC42), resulting in down regulation of its protein expression together with that of MMP-2 and MMP-9." (PMID 24670365, 2014). "In addition, MMP9 acts as a sheddase of HER2, and an increase in circulating HER2 through shedding may be an essential factor in development of resistance to chemotherapy, including Ttzm resistance, in advanced breast cancer." (PMID 25499743, 2014). "Furthermore, these data also demonstrate that 1–4 freeze/thaw cycles, which corresponds to the number of cycles for the analysed breast cancer samples, do not affect the levels of MMP-9:TIMP-1 complex, thereby eliminating the concern of complex degradation upon repeated freeze/thaw cycles." (PMID 24330623, 2013).
breast carcinoma (continued). "However, after inhibiting mRNA levels of MTA1, protein expression of ER alpha, MMP-9, cyclinD1 and the changes of cancer cells invasiveness, proliferation, cells cycle were no statistical difference in ER-positive human breast cancer cell lines MCF-7 (P > 0.05)." (PMID 21595884, 2011). "Since MMP9 is well known as a negative prognostic indicator, the association of low MMP9 with high p-ERK1 levels fits to our result that high ERK activity is associated with long recurrence-free survival times in breast cancer, although it is no proof of a causal relationship between both factors." (PMID 15928662, 2005). "In a canine mammary tumor model, TGF-β/Smad pathway activation was significantly correlated with MMP9 overexpression, and MMP9 further amplified pathway activity via a negative feedback mechanism." (PMID 40646747, 2025). "In human breast cancer, the MMP-9 x LCN2 complex was first identified by antibody detection and has been found in the urine of breast cancer patients as opposed to healthy individuals." (PMID 39188682, 2024). "Analyzed by quantitative real-time PCR, nicardipine decreased MMP-9 mRNA expression in a dose-dependent manner; however, MMP-2 expression was not affected by nicardipine in 4T1, JC, and MDA-MB-231 breast cancer cells." (PMID 34483918, 2021). "Both MMP-9 and CK19 are considered negative prognostic markers, but the effect of CK19 in breast cancers seems to be more complex and ambiguous." (PMID 34884588, 2021). "BAALC overexpression led to an increase in the expression of active MMP-9, but not active MMP-2, compared to EV expressing MCF-7 breast cancer cells." (PMID 33968759, 2021). "Moreover, through TIMER2.0 analysis, it was found that MMP9 had a significant positive correlation with CD4+ T cells, dendritic cells, macrophages, and neutrophils, indicating that MMP9 may be involved in the immune cell infiltration process of breast cancer tissues." (PMID 35069702, 2021). "Luteolin, but not its glycosides, suppresses TPA-induced MMP-9 expression and inhibits migration and invasion in MDA-MB-231 breast cancer cells." (PMID 31611756, 2019). "Unlike hormone-responsive breast cancer cells (MCF-7 and T47D), TNBC cells (MDA-MB-231, HCC-1973, and Hs578T) expressed higher levels of both MMP-2 and MMP-9." (PMID 30185799, 2018). "Report of transient expression of SNCG in human breast cancer cells MDA-MB-435 and a recent study of stable expression of SNCG in colon cancer cells LS 174T did not alter the secretion of MMP2 or MMP9 in the CM." (PMID 29903032, 2018). "In a mouse model of breast cancer based on MCF-7 cells that do not endogenously express MMP9 and into which an adenovirus vector containing the MMP9 gene was injected, tumor regression was induced." (PMID 30174795, 2018). "Despite the fact that MMPs are key regulators of invasion in prostate cancer cells, our results indicate that MMP9 is not a target of Foxy-5 in DU145 prostate cancer cells, which is in contrast to breast cancer cells." (PMID 28886116, 2017). "Here we report that in non-metastatic, estrogen receptor-positive breast cancer (ER+ BC) cells, induced MLK3 expression robustly upregulates the oncogenic transcription factor, FOS-related antigen-1 (FRA-1), which is accompanied by elevation of matrix metalloproteinases (MMPs), MMP-1 and MMP-9." (PMID 28604765, 2017). "For instance, co-culture of macrophages with ovarian or breast cancer cell lines was found to increase the expression of MMP2 and MMP9 in macrophages, but not in tumor cells, to promote tumor invasiveness." (PMID 27487154, 2016). "We observed that MMP-2 and MMP-9 activities, among other MMP activities, are increased in metastatic breast cancer cell lines, xenografts, and lungs as compared with non-metastatic lines." (PMID 28721370, 2015).
breast carcinoma (continued). "The difference in MMP-9 expression between the BCYW and BCMEW groups was statistically significant, while the difference in VEGF-C expression between the two breast cancer groups was not statistically significant." (PMID 26656588, 2015). "Accordingly, it has been demonstrated that the therapeutic effects of doxorubicin were decreased in KO mice lacking MMP-9, and interestingly, MMP-9 expression is increased in tumors of the MPA breast cancer model treated with MFP." (PMID 24912774, 2014). "Therefore we addressed this by studying the complex of TIMP-1 and pro-MMP-9/MMP-9 and in the present study of 465 breast cancer patients we were not able to find support for the hypothesis that the concentration of MMP-9:TIMP-1 complexes is indicative of prognosis in breast cancer patients." (PMID 24330623, 2013). "Previous studies have shown that the expression of MMPs, including MMP9, can be upregulated by MDM2, although this has not been show in breast cancer to date." (PMID 24236052, 2013). "We have previously shown that splenic macrophages from mammary tumor-bearing mice secrete higher levels of the pro-angiogenic molecules CCL2, CXCL2, and MMP-9 (compared to non-tumor bearers) and that CHI3L1 stimulates this increased production." (PMID 24399973, 2013). "Conversely, it has been shown in pancreatic cancer cells that QSOX1 favored the activities but not the secretion of MMP-2 and MMP-9; whereas, QSOX1, in our breast cancer cell models, decreases both the activity and secretion of these MMPs." (PMID 23098186, 2012). "Other investigators have reported that α-mangostin exerts inhibitory effects on cell invasion and migration in mammary cancer cells due to downregulation of MMP-2 and MMP-9, and we cannot preclude that this mechanism was not operating in our study, as well." (PMID 21639868, 2011). "A study demonstrated that exosome, rich in ECM degradation enzyme, transferred from MDA-MB-231 highly metastatic breast cancer cells to MCF-10A epithelial breast cancer cells (non-tumorigenic), leads to metastasis by increasing the expression of MMP-2 and MMP-9." (PMID 37046817, 2023). "Further, ar-turmerone was reported to efficiently inhibited 12-O-tetradecanoylphorbol-13-acetate (TPA) induced invasion, colony formation, migration, stimulated matrix metalloproteinase (MMP-9), and cyclooxygenase-2 (COX-2) in breast cancer cells at non-cytotoxic concentrations." (PMID 30609771, 2019). "MMP9 is not a predicted target gene of miR-146 in human or zebrafish, but human MMP9 was found to be down-regulated upon miR-146a/b overexpression in MDA-MB-231 breast cancer cells and in THP-1 macrophages." (PMID 24112639, 2013). "However, in ER alpha-positive breast cancer cells MCF-7, protein expression levels of ER alpha, MMP-9 and CyclinD1 had no distinct difference in three groups(P > 0.05)." (PMID 21595884, 2011). "In correlation with this hypothesis, recent studies show that the expression of metalloprotease MMP9 from the tumour surrounding stroma, unlike its expression in tumour cell cytoplasm, correlates with unfavourable prognosis in ERBB2 positive breast cancer." (PMID 19183447, 2009). "Given our finding that subcutaneous injection of tumour cells into mice simultaneously with human proangiogenic monocytes boosted the development of the colon carcinomas DLD1 and HCT116 but not the breast carcinoma SKBR7, we investigated whether tumour cell-derived inhibitors would block MMP9." (PMID 29367702, 2018). "In breast cancer cells, the specific induction of active BMP-4 is exclusively observed in breast cancer cells expressing NDRG2 but not in control breast cancer cells, and NDRG2 expression inhibits the mRNA expression of several MMPs and the gelatinolytic activity of MMP9." (PMID 26506239, 2016).
Stroke (450 papers, 2005 to 2026). Sudden impairment of blood flow to a part of the brain due to occlusion or rupture of an artery to the brain. "Pro-inflammatory factors secreted by neutrophils, such as TNF-α and IL-6, promote the expression of MMP-9, which exacerbates endothelial damage in cerebral vessels following stroke and increases the risk of hemorrhagic complications." (PMID 40697574, 2025). "MMP-9 in extracellular vesicles was significantly elevated within 133 min after stroke, and baseline serum MMP-9 levels were associated with cognitive impairment at 3 months after stroke." (PMID 40821836, 2025). "Neutrophils synthesize and secrete pro-inflammatory factors such as TNF-α, IL-1β, and IL-6 and promote the expression of MMP9, which aggravates cerebrovascular endothelial cell injury after stroke and increases the risk of hemorrhagic complications." (PMID 38740617, 2025). "A meta-analysis further supported MMP-9 as a sensitive and specific biomarker for predicting the risk of HT after thrombolysis or stroke." (PMID 39606238, 2024). "MMP-9 has also been linked with inflammatory responses in various diseases, including myocardial infarction, stroke, Alzheimer’s disease, multiple sclerosis, and tumors." (PMID 39273389, 2024). "The level of MMP-9 activity has been implicated in various vascular and neurological conditions, including its association with stroke volume." (PMID 38255970, 2024). "MMP-9 has shown potential as a predictor of stroke prognosis, supported by clinical studies demonstrating that higher plasma MMP-9 levels are associated with more severe strokes and an increased risk of poor functional outcomes." (PMID 39606238, 2024). "The inflammatory factor matrix metalloproteinase-9 (MMP-9) was elevated after stroke and has been implicated in aggravating blood-brain barrier disruption, neuronal death, myelin degradation and white matter injury." (PMID 38720885, 2024). "Elevated MMP-9 levels, often linked to pathological conditions like post-stroke epilepsy, position it as a valuable biomarker for predicting the development of epilepsy." (PMID 38255970, 2024). "At the same time, there is good evidence of MMP-9 upregulation in human brain tissues and in the blood after stroke, and increased blood levels are linked to late hemorrhagic transformation." (PMID 39273389, 2024). "Our findings do not confirm previous reports indicating an association between serum MMP-9 levels and post-stroke depression." (PMID 37371326, 2023). "In Indian patients with IS, CT genotype, TT genotype and T allele were significantly more frequent in patients with stroke, but MMP-9 methylation was identified as a protective factor." (PMID 36835040, 2023). "Overall analysis showed that MMP-9 gene rs3918242 polymorphism significantly increases stroke risk (T vs. C; TT vs. CC; CT vs. C; TT + CT vs. CC; TT vs. CT + CC; all p < 0.05)." (PMID 37206663, 2023). "Although MMP-9 involved in the degradation of the extracellular matrixes is considered to cause cerebral damage after stroke, studies confirm that MMP-9 also plays a role in synaptic plasticity and synapse remodeling." (PMID 37371326, 2023). "A recent study suggests that elevated serum MMP-9 levels in the acute phase of ischemic stroke were related to increased risk of post-stroke depression within three months, suggesting that MMP-9 has a prognostic role." (PMID 37371326, 2023). "Matrix metalloproteinases, in particular MMP-9, play a critical role in the stroke-associated BBB disruption, hemorrhagic transformation, and neuroinflammation after stroke." (PMID 35309561, 2022). "MMP-9 in particular has been shown to be a key factor in the disruption of the blood-brain barrier following strokes and is associated with stroke severity." (PMID 35547443, 2022). "Meta-analyses of independent genomic studies support an association of polymorphisms of the VEGF and MMP-9 genes with increased risk of stroke." (PMID 36333663, 2022).